GIPR (gastric inhibitory polypeptide receptor)
Diseases named in the same sentence as GIPR in open-access papers (continued):
Sharing a sentence is not in itself a finding about the gene and the disease.
Insulin resistance (27 papers, 2011 to 2025). Increased resistance towards insulin, that is, diminished effectiveness of insulin in reducing blood glucose levels. "The C allele of rs13389219 near GRB14 (p = 0.026) and A allele of rs10423928 in the intron of the GIPR gene (p = 0.012) showed worse insulin resistance (increased HOMA2-IR)." (PMID 30089489, 2018). "Several GWAS have identified variants positioned in the GIPR locus, including the E354Q GIPR variant, to associate with increased 2-h glucose levels, decreased insulin secretion, insulin resistance and risk of T2D, further supporting the importance of the GIP-GIPR axis in glucose regulation." (PMID 34760890, 2021). "Animal studies have demonstrated that GIPR agonists can ameliorate insulin resistance independently of body weight changes and enhanced insulin sensitivity in white adipose tissue is associated with reduced hepatic lipid deposition." (PMID 41431568, 2025). "In rodents and humans, WAT expresses the transcript encoding GIPR; the level is higher in visceral adipose tissue compared to subcutaneous adipose tissue, and the GIPR transcript is downregulated under insulin resistance." (PMID 40892365, 2025). "GIPR signaling in adipose tissue has been suggested to play an important role in HFD-induced insulin resistance and hepatic steatosis through adipose tissue-specific GIPR knockout mice." (PMID 39940910, 2025). "A recent paper by Yamane & Harada indicates an important role of GIPR signaling in adipose tissue in high fat diet -induced insulin resistance and hepatic steatosis in vivo." (PMID 32069846, 2020). "It has been shown that in obese individuals, insulin resistance reduces gastric inhibitory polypeptide receptor expression and GIP activity in subcutaneous adipose tissue but not in visceral adipose tissue." (PMID 31477157, 2019). "Here, we found that methylation of GIPR promoter in blood was negatively correlated with a surrogate marker of insulin resistance (HOMA-IR) and fasting glucose." (PMID 24086540, 2013). "Hypomethylation of GIPR promoter correlated with higher fasting glucose and insulin resistance in T2D patients." (PMID 24086540, 2013). "Further research is needed to define the role of methylation changes in GIPR promoter in adipose tissue and their potential impact on insulin resistance." (PMID 24086540, 2013). "We also found that GIPR promoter was hypomethylated in T2D patients as compared to controls, as well as, new correlations between insulin resistance, fasting glucose and GIPR promoter methylation in DNA from peripheral blood." (PMID 24086540, 2013). "Recent papers underlie an important role of GIPR signaling in adipose tissue in HFD-induced insulin resistance and hepatic steatosis in vivo with no direct effect on fat accumulation." (PMID 32069846, 2020). "It was previously reported that aged GIPR-knockout mice show improvement of insulin resistance and reduced fat mass without a reduction of body weight compared to aged WT mice under normal diet feeding condition." (PMID 31977316, 2020). "Additionally, different studies have proposed potential DNA methylation biomarkers in relation to plasma insulin levels, insulin secretion and insulin resistance such as those located in PPARGC1A, HTR2A, LY86, TFAM, GIPR, ADIPOQ, and IGFBP3 genes." (PMID 31208038, 2019). "Impaired activation of GIPR and GLP-1R contributes to a decrease in the secretion of insulin and ghrelin and, on the contrary, to an increase in leptin and glucagon in the circulation, which contributes to the formation of insulin resistance in obese patients with T2DM." (PMID 33959145, 2021).
Hyperglycemia (17 papers, 2012 to 2026). An increased concentration of glucose in the blood. "The researcher suggested that the hyperglycemia-induced downregulation of GIPR expression may be closely associated with ubiquitination." (PMID 36860432, 2022). "Several studies, including ours, have shown that exposure to hyperglycemia decreased the gene or protein levels of GIPR in HUVECs and several types of monocytes/macrophages." (PMID 32098413, 2020). "Indeed, the idea that the insulinotropic actions of GIP are absent in subjects with T2D29 has stalled the development of GIPR agonists as a therapy for hyperglycemia." (PMID 37277609, 2023). "Moreover, the reduced GIPR expression levels in ZDF rats were relieved following normalization of hyperglycemia by phlorizin treatment." (PMID 36860432, 2022). "It has been reported that an improved control of hyperglycemia may reverse GIPR expression downregulation and resistance to GIP in Zucker rats." (PMID 26221611, 2015). "However, influence of hyperglycemia on GIPR expression in vascular cells is controversial." (PMID 32098413, 2020). "It was reported that hyperglycemia and persistent depolarization of β-cells led to GLP-1R’s signaling switch from Gs to Gq, whereas GIPR continued to rely on Gs." (PMID 38376482, 2024). "Overall, these data indicate that agonism of GLP-1R or GIPR, individually or in combination, does not affect fatty acids in hepatocytes in response to OA and the combination of OA with palmitic acid or in conditions of hyperglycemia and hyperinsulinemia." (PMID 39607493, 2024). "Given that the effect of GIP on insulin secretion is diminished or absent during hyperglycemia, but our TCF7L2 x GIPR interaction seems to impact insulin secretion during the whole hyperglycemic clamp, a role of an acute GIP effect is not probable." (PMID 30846969, 2019).
Cushing syndrome (10 papers, 2009 to 2025). Cushing's syndrome (CS) encompasses a group of hormonal disorders caused by prolonged and high exposure levels to glucocorticoids that can be of either endogenous (adrenal cortex production) or exogenous (iatrogenic) origin. "The molecular etiology behind a rare subtype of Cushing syndrome caused by ectopic expression of glucose-dependent insulinotropic polypeptide receptor (GIPR) was unveiled; microduplications at chromosome 19q13 that contain the GIPR locus." (PMID 29794126, 2018). "The ectopic expression of GIPR in the human adrenal gland causes significant hypercortisolemia after ingestion of a meal and leads to food-dependent Cushing’s syndrome (FD-CS), demonstrating that activation of human GIPR is capable of robustly activating adrenal glucocorticoid secretion." (PMID 25334044, 2014). "On the other hand, the neoplastic transformation in primary bilateral macronodular adrenal hyperplasia (PBMAH) involves the ectopic expression of GIPR, which is necessary and sufficient for this condition to occur." (PMID 37344722, 2024). "For example, ectopic expression of the gastric inhibitory polypeptide receptor (GIPR) in the human adrenal gland causes significant hypercortisolemia after meal ingestion and leads to Cushing’s syndrome." (PMID 26106367, 2015). "In GIP-dependent primary bilateral macronodular adrenal hyperplasia with Cushing’s syndrome, KDMIA mutations were found to be responsible for ectopic GIPR expression but could also result in increased expression of LHCGR." (PMID 36926028, 2023). "Acromegaly patients with GIPR expression commonly react to oral glucose load with a paradoxical increase in GH level, which resembles the induction of hormone secretion in food-dependent Cushing’s syndrome." (PMID 36497102, 2022). "G-protein-coupled receptors responding to LH, glucose-dependent insulinotropic peptide (GIPR), serotonin, vasopressin, and glucagon have been identified in some humans with ACTH-independent Cushing's syndrome." (PMID 30356827, 2018).
insulinoma (8 papers, 2017 to 2025). "The rat GIP receptor (rGIPR) was cloned in 1993 from cDNA libraries of rat cerebral cortex and rat insulinoma RINm5F cells, characterizing GIPR as a seven-transmembrane G protein-coupled receptor (GPCR) of the class B (a.k.a. secretin receptor) family." (PMID 40024571, 2025). "Of importance, we demonstrated GIPR-mediated binding in sections from human insulinoma and ileum NENs." (PMID 36678558, 2022). "The GIPR was firstly identified in transplantable insulinoma and insulin-secreting β cell line of hamster." (PMID 36860432, 2022). "The 68Ga-labeled bioconjugate was evaluated in vitro in terms of binding affinity, specificity, and internalization in HEK293 cells transfected with the human GIPR, GLP1, or GCG receptors and in sections of human insulinoma and NENs." (PMID 36678558, 2022). "We used incretin-responsive rat insulinoma-derived INS-1 832/3 cells, in which we first confirmed expression of GLP-1R, GIPR, and GCGR by qPCR." (PMID 33268378, 2021). "In these tumor entities, GIPR levels gradually increase in a subset of insulinomas and non-functioning pancreatic NENs." (PMID 38730608, 2024). "Incretin receptors, including glucagon-like peptide-1 (GLP-1R) and glucose-dependent insulinotropic polypeptide receptor (GIPR), have been investigated with earnest in recent years, with putative utility in tumors such as insulinoma that often occur with low or absent expression of SSTR." (PMID 29255447, 2017).
neuroendocrine tumors (7 papers, 2015 to 2024). "Recently, alterations in GIPR expression have been reported in neuroendocrine tumors, neuroendocrine neoplasms, and medullary thyroid cancer, suggesting a clinically significant diagnostic and prognostic potential." (PMID 38730608, 2024). "In neuroendocrine neoplasms (NENs), high GIPR expression likewise correlates with a high tumor grade." (PMID 38730608, 2024). "Moreover, GIPR is significantly overexpressed in various neuroendocrine tumors (NETs) compared to normal tissue." (PMID 38730608, 2024). "Otherwise, the effects might be tissue-dependent, as very high GIPR levels in neuroendocrine tumors have been observed to either increase or decrease raised proliferation levels, depending on the tumor site." (PMID 38730608, 2024). "Recently, we have confirmed that the aberrant expression of GIPR is an early event in the neoplastic transformation in medullary thyroid cancer, which present a high tumor-to-normal tissue ratio (T/N ratio) for GIPR, like most neuroendocrine tumours." (PMID 37344722, 2024). "GIPR, which is highly expressed in group 1 tumors, encodes the receptor of glucose-dependent insulinotropic polypeptide (GIP) that has a well-known role in neuroendocrine tumors." (PMID 36497102, 2022). "Imaging and radiotherapy targeting the glucose-dependent insulinotropic polypeptide receptor (GIPR) could potentially benefit the management of neuroendocrine neoplasms (NENs), complementing clinically established radiopharmaceuticals." (PMID 36678558, 2022). "GIPR, short for gastric inhibitory polypeptide receptor, has been regarded as a promising target for imaging and therapy in gastric and neuroendocrine tumors, and it has also been reported that GIPR is significantly overexpressed in stomach tissue compared with normal tissue." (PMID 34354996, 2021). "In food-dependent Cushing’s syndrome (FDCS), the ectopic expression of GIPR has been associated with the inversed rhythm of cortisol secretion, while in neuroendocrine tumors (NET), the incidence/density of GIPR may correlate with increasing proliferative rates and the development of metastasis." (PMID 37298217, 2023).
acromegaly (6 papers, 2022 to 2025). Acromegaly is an acquired disorder related to excessive production of growth hormone (GH) and characterized by progressive somatic disfigurement (mainly involving the face and extremities) and systemic manifestations. "Most of these tumors also exhibited paradoxical increase of GH in response to an oral glucose tolerance test, a phenomenon observed in a specific group of patients with acromegaly as a result of ectopic expression of GIPR." (PMID 40813692, 2025). "Collectively, the high expression of GIPR in PIT1/SF1 tumors may account for higher IGF-1 levels than in PIT1 tumors in acromegaly." (PMID 40421250, 2025). "Introducing targeted therapy to antagonize the GIPR on GIPR-expressing somatotroph adenomas could represent a novel treatment approach for acromegaly patients with a paradoxical GH response pattern to OGTT." (PMID 39194755, 2024). "Therefore, GIPR+ somatotroph adenomas had higher baseline serum IGF-1 levels than GIPR- adenomas." (PMID 40421250, 2025). "Transcriptomic group 1 includes ~20% of acromegaly patients with GNAS mutations-negative, mainly densely granulated tumors that co-express GIPR and NR5A1 (SF-1)." (PMID 36497102, 2022). "These PIT-1/SF-1 positive sPitNETs differ in several aspects from other acromegaly-associated PitNETs lacking SF-1 expression: they are densely granulated adenomas without GNAS mutations, with ectopic GIPR expression, a distinctive DNA methylation profile, and high level of genomic instability." (PMID 40813692, 2025). "Since GIPR mediates the paradoxical response in more than 80% of somatotropinomas it can be hypothesized that, at least in some cases of the non-acro↑IGF−1 group, the GH-Par may represent an early indicator of acromegaly." (PMID 37344722, 2024).
Glucose intolerance (6 papers, 2008 to 2025). Glucose intolerance (GI) can be defined as dysglycemia that comprises both prediabetes and diabetes. "The HFD mice develop glucose intolerance within a week that coincided with reduction in expression of SetD7 along with previously reported decreased expression of MafA, Glut2, Gck, GIPR, and PPARγ in islets." (PMID 34592314, 2021). "Whereas GIPR−/− animals show glucose intolerance on normal chow, the more recent work of McClean and colleagues show improvement of these parameters with their antagonists in severely obese mice after prolonged high fat feeding." (PMID 18779862, 2008). "In fact, GIPR−/− mice have been reported to display signs of glucose intolerance." (PMID 18779862, 2008). "Nonetheless, although mice with GIPR signal inhibition in the PNS do not show alterations in body weight and remain fully sensitive to weight loss induced by GIPR antagonism, these mice develop glucose intolerance with impaired glucose-induced secretion of insulin and GIP when fed a HFD." (PMID 40301583, 2025).
Hepatic steatosis (6 papers, 2020 to 2026). Steatosis is a term used to denote lipid accumulation within hepatocytes. "Finally, perhaps someone with fatty liver disease would benefit more from a GLP‐1R/GCGR co‐agonist than an agent targeting GIPR, if equally efficacious for weight loss." (PMID 41287212, 2026). "The inhibition of GIPR signaling in adipose tissue decreased body weight and reduced hepatic steatosis in HFD-fed mice." (PMID 39940910, 2025). "In conclusion, combined GIPR/GLP1R agonism additively attenuates hepatic steatosis and lowers hepatic inflammation, ameliorating liver injury during the development of NAFLD in E3L.CETP mice." (PMID 37379656, 2023). "In addition to attenuating hepatic steatosis, combined GIPR/GLP1R agonism strongly lowered hepatic inflammation as evidenced by a decreased number of moKCs possibly as a result of lowered expression of hepatic chemokines involved in leukocyte trafficking to the liver." (PMID 37379656, 2023). "We interpretate that GIPR and GLP1R agonism additively attenuate hepatic steatosis, lower hepatic inflammation, ameliorate liver injury, together preventing NAFLD development in humanized APOE∗3-Leiden.CETP mice." (PMID 37379656, 2023). "The current study in humanized E3L.CETP mice demonstrates that GIPR and GLP1R agonism additively attenuate hepatic steatosis, lower inflammation and ameliorate liver injury in the context of HFHC diet-induced NAFLD development." (PMID 37379656, 2023). "We demonstrate that GIPR and GLP1R agonism additively attenuate hepatic steatosis, lower inflammation, ameliorate liver injury, and together prevent the development of NAFLD." (PMID 37379656, 2023). "The anti-inflammatory effects of GIPR and GLP1R agonism may be indirect and a consequence of attenuated hepatic steatosis, as lipid accumulation in itself is a potent inducer of inflammation." (PMID 37379656, 2023). "Besides lowering food intake, we observed that GIPR and GLP1R agonism exerted a synergistic effect on increasing fecal energy and lipid excretion, which likely contributed to the attenuated hepatic steatosis through lowering lipid availability." (PMID 37379656, 2023). "Preclinical studies suggest that tirzepatide, a dual GLP-1/gastric inhibitory polypeptide receptor agonist may offer superior metabolic benefits compared to conventional GLP-1 agonists by improving β-cell function, enhancing insulin sensitivity, and reducing fatty liver progression." (PMID 40430489, 2025). "In the current study GIPR and GLP1R agonism additively lowered food intake and body weight confirming previous reports in mice, which may at least in part explain the additive reduction of hepatic steatosis upon treatment with both agonists as it lowers the flux of nutrients towards the liver." (PMID 37379656, 2023). "As the receptor for GIP (GIPR) is not found to be expressed on hepatocytes, the suggested relation of GIP with fatty liver disease may involve its direct and indirect influence on nutrients’ metabolism, as well as interactions with other endocrine factors regulating liver function." (PMID 32069846, 2020).
atherosclerosis (5 papers, 2012 to 2025). A disease characterized by the build-up of fatty material and calcium deposition in the arterial wall resulting in partial or complete occlusion of the arterial lumen. "CETP mice, a transgenic mouse model with accelerated atherosclerosis, showed that combined GIPR/GLP1R agonism attenuated the development of severe atherosclerotic lesions." (PMID 39834741, 2024). "We know that GIPR mediated this anti-atherogenic effect, because co-infusion of GIPR antagonist abolished the GIP-induced suppression of atherosclerosis." (PMID 22536426, 2012). "We recently reported that GIP infusion remarkably suppressed the development of atherosclerosis in STZ-induced diabetic Apoe−/− mice, and GIP suppressed macrophage foam cell formation obtained from the diabetic mice though GIPR was mildly down-regulated in the macrophage." (PMID 23967137, 2013).
adenoma (4 papers, 2023 to 2025). A neoplasm arising from the epithelium. "In the future, targeting pituitary GIPR antagonist could be a medical alternative for these adenomas." (PMID 36968144, 2023). "GIPR-expressing adenomas are negative for activating GNAS mutations, display particular features, and respond better to somatostatin analogues." (PMID 36968144, 2023).